SERPINA1 (serpin family A member 1)
Diseases named in the same sentence as SERPINA1 in open-access papers (continued):
Sharing a sentence is not in itself a finding about the gene and the disease.
myocardial infarction (12 papers, 2011 to 2025). Gross necrosis of the myocardium, as a result of interruption of the blood supply to the area, as in coronary thrombosis. "Further, SERPINA1 is involved in the immune response by inhibiting ATP-induced interleukin-ß-release and secreted into the bloodstream in response to myocardial infarction." (PMID 38379859, 2023). "In another study, low levels of SERPINA1, PLG, KLKB1, ITIH4, and APOL1 in serum of patients with lacunar stroke were associated with poor prognosis and increased risk of recurrent stroke or myocardial infarction and cognitive decline." (PMID 31242583, 2019). "Six hub genes, including BCL3, HCK, PPIF, S100A9, SERPINA1, and TBC1D9B that differentiated on admission after myocardial infarction the HF patients from the non-HF ones, can serve as early prognostic biomarkers of post-AMI patients." (PMID 31850068, 2019).
pancreatic cancer (12 papers, 2008 to 2025). "Their research revealed a significant relationship between fucosylated SERPINA1 levels, the stage of pancreatic cancer, and patient prognosis." (PMID 39372389, 2024). "Elevated SERPINA1 fucosylation was found to be positively correlated with TNM stage of pancreatic cancer, with high SERPINA1 indicating a poor prognosis." (PMID 38396140, 2024). "This discovery highlights the potential of fucosylated SERPINA1 as a novel biomarker for diagnosing pancreatic cancer." (PMID 39372389, 2024). "SERPINA1 belongs to the serine protease inhibitor superfamily, and it has been studied as a target of abnormal protein fucosylation in pancreatic cancer." (PMID 38396140, 2024). "Overexpression of c-Myc would also increased expression of Serpina1 in metastatic pancreatic cancer, which was consistent with our conclusions." (PMID 37161577, 2023). "Intriguingly, we observed highly upregulated expression of Igfbp1 and Serpina1 in liver metastatic tissues compared to primary pancreatic tumors and normal pancreas." (PMID 18218118, 2008). "We identified Igfbp1, Serpina1 and Wt1 genes that are likely to be clinically useful biomarkers for prognostic or therapeutic purposes in metastatic pancreatic cancer, particularly in pancreatic cancer where c-Myc is overexpressed." (PMID 18218118, 2008). "SERPINA1 is up-regulated in PDA tissue and serum and has been proposed as a prognostic factor in pancreatic cancer." (PMID 32245227, 2020). "CLUSTER1 also included up-regulated genes with unknown importance in pancreatic cancer, such as MATN3, SERPINA1, and IGFBP5." (PMID 33194391, 2020). "Verification of Igfbp1 and Serpina1 by RT-PCR and quantitative PCR showed strong expression in liver metastatic lesions but there was a lack of expression of these genes in primary pancreatic tumors or normal pancreas." (PMID 18218118, 2008).
pneumonia (12 papers, 2006 to 2026). An acute, acute and chronic, or chronic inflammation focally or diffusely affecting the lung parenchyma, caused by an infection in one or both of the lungs (by bacteria, viruses, fungi, or mycoplasma.). "Drug-target analyses suggested that modulation of the complement and coagulation cascades may benefit pneumonia patients with comorbid LC or COPD, highlighting CFB, SERPINA1, and SERPING1 as key candidates and pointing to monocyte-centered pathways as promising therapeutic directions." (PMID 41624060, 2026).
preeclampsia (12 papers, 2016 to 2024). Preeclampsia is a hypertensive disorder of pregnancy that is characterized by new-onset hypertension with proteinuria presenting after 20 weeks of gestation, and depending on mild or severe forms may initially present with severe headache, visual disturbances, and hyperreflexia. "This allows attributing preeclampsia to a wide cohort of pathologies associated with pathological aggregation of a particular protein (in particular, SERPINA1)." (PMID 32019243, 2020). "Estimation of SERPINA1 in urine can be used as a diagnostic test for the severity of preeclampsia with very high specificity." (PMID 32019243, 2020). "Urinary excretion of PE specific SERPINA1 peptides was linked with the most severe forms of preeclampsia in clinical manifestations, primarily the level of systolic hypertension and proteinuria." (PMID 32019243, 2020). "Thus, detection of SERPINA1 in urine can be used as a diagnostic test for the severity of preeclampsia." (PMID 32019243, 2020). "Two such markers are fragments of SERPINA1 and albumin, upregulated in women with preeclampsia but downregulated in gestational hypertension." (PMID 36909346, 2023). "The majority of the family members have been confirmed to be closely related to preeclampsia, such as SerpinA1, A3, E1, and F1." (PMID 34648566, 2021). "An increase in expression of SERPINA1 in the structural elements of the placenta during preeclampsia reflects a protective mechanism against hypoxia." (PMID 32019243, 2020). "The decrease in the glomerular filtration rate in severe preeclampsia correlated with the level of SERPINA1 peptides in the urine in PE along with sFLT/PLGF." (PMID 32019243, 2020). "With an increase in expression of SERPINA1, the structural elements of the placenta during preeclampsia reflect a protective mechanism with an increase in protease inhibitors under hypoxia." (PMID 32019243, 2020). "SERPINA1, a serine protease inhibitor, is actively studied in the context of preeclampsia (PE)." (PMID 39408980, 2024). "A previous study showed that SERPINA1 peptides in urine could be used as potential markers for diagnosing the severity of preeclampsia." (PMID 37009470, 2023). "In severe preeclampsia, as previously shown by electron microscopy, damage to the structures of the placenta, especially the trophoblast membranes, results in the release of SERPINA1 granules from the cytoplasm of the cyto- and syncytiotrophoblast into the maternal duct." (PMID 32019243, 2020). "Clinical differences between the PE groups with/without SERPINA1 peptides in urine (PE_SER+/PE_SER−) are associated with the level of systolic blood pressure, proteinuria, severe proteinuria, and the frequency of severe forms of preeclampsia." (PMID 32019243, 2020). "Moreover, urinary SERPINA1 peptides detection is important to differentiate CAH and superimposed PE (PE with CAH) with real preeclampsia." (PMID 32019243, 2020).
sarcoidosis (12 papers, 2009 to 2025). Sarcoidosis is a multisystemic disorder of unknown cause characterized by the formation of immune granulomas in involved organs. "The relative gene expression levels for ATP6AP1, CYBB, LAMP2, and SERPINA1 were significantly higher in sarcoidosis monocytes as compared to healthy monocytes." (PMID 28577019, 2017). "Similarly, assessment of SERPINA1 led to diagnostic accuracy (expressed in AUC) of 0.8375, 0.7050 and 0.7200, respectively, to discriminate between IPF and healthy controls, IPF and sarcoidosis, and IPF and hypersensitivity pneumonitis." (PMID 28122020, 2017). "The serum concentrations of HBB, CRP and SERPINA1 in IPF, sarcoidosis and hypersensitivity pneumonitis patients were higher compared to the healthy control group." (PMID 28122020, 2017).
Stroke (12 papers, 2015 to 2024). Sudden impairment of blood flow to a part of the brain due to occlusion or rupture of an artery to the brain. "Our study identified four proteins (ceruloplasmin, SERPINA1, vWF, and F13B) that commonly differentiated total stroke, IS, and ICH from healthy control subjects." (PMID 36237606, 2022). "In fact, SERPINA1 expression has been shown to increase during hypoxic conditions, and hypoxia-related tissue damage during ischemia-reperfusion injury, stroke, ischemic heart disease has been lowered by the therapy with AAT." (PMID 31487965, 2019). "Four proteins [ceruloplasmin, alpha-1-antitrypsin (SERPINA1), von Willebrand factor (vWF), and coagulation factor XIII B chain (F13B)] commonly differentiated total stroke, IS, and ICH from healthy control subjects." (PMID 36237606, 2022).
thyroid cancer (12 papers, 2011 to 2025). "SERPINA1 further associates with lymph node metastasis and immune cell infiltration in thyroid cancer." (PMID 40821817, 2025). "In a study related to thyroid cancer, SERPINA1 was found to be associated with lymph node metastasis of thyroid cancer and significantly associated with immune cell infiltration." (PMID 38710698, 2024). "Bioinformatics analysis of RNA-sequencing data suggested that HSF2 may be associated with the development of thyroid carcinoma by regulating SERPINA1 and FOSB expression." (PMID 34917120, 2021). "Through this analysis, they thought that HSF2 is involved in thyroid carcinoma development by regulating SERPINA1 and FosB genes." (PMID 36430241, 2022). "Bioinformatics analysis has demonstrated that HSF2 may be involved in the oncogenesis of thyroid carcinoma by mediating the expression of SERPINA1 and FOSB." (PMID 35087869, 2021). "We were unable to find any reports of changes in SERPINA5 expression in thyroid cancer, although several studies reported over-expression in SERPINA1 (belonging to the same gene cluster on human chromosome 14q32.1) in sporadic and radiation-related thyroid cancers." (PMID 23520464, 2013). "Concurrently, SERPINA1 and TACSTD2 show peak expression in tissue stem cell phases, suggesting their cooperative regulation of stem-like malignant properties in thyroid cancer." (PMID 40520228, 2025). "Some proteins' alteration was found in thyroid cancer, such as CK19, TG, Ki67, Calcitonin, TTF-1, BRAF, RET, HBME-1, SERPINA1, TfR1/CD71, FHL1 and galectin-3." (PMID 22188859, 2011). "Moreover, there was no study on expression level of SERPINA5 in thyroid cancer, although some studies reported over-expression in SERPINA1 in sporadic and radiation-related thyroid cancers (Brenneret al., 2013; Sobhanet al., 2020)." (PMID 34837923, 2021).
acute kidney injury (11 papers, 2014 to 2026). Sudden and sustained deterioration of the kidney function characterized by decreased glomerular filtration rate, increased serum creatinine or oliguria. "Further, the most differentially abundant proteins found to be associated with renal failure were serotransferrin (TF), alpha-trypsin 1 (SERPINA1), alpha-1B-glycoprotein (A1BG), and NHL repeat-containing protein 3 (NHLRC3)." (PMID 38536893, 2024). "Although high levels of SERPINA1 have been found in acute kidney injury patients and nephrotic syndromes, such as glomerulonephritis, this protein is also associated with a protective role in maintaining kidney membrane integrity." (PMID 38536893, 2024). "Increased SERPINA1 levels in serum have been reported in inflammatory diseases including acute kidney injury, glomerulonephritis, minimal change disease, and focal segmental glomerulosclerosis." (PMID 37686344, 2023). "Among these proteins, levels of β-2-microglobulin (B2M) and α-1-antitrypsin (SERPINA1) are increased during sepsis-induced acute kidney injuries (AKI) while levels of α fibrinogen (FGA) chains are decreased." (PMID 33425215, 2020). "Increased serum levels of SERPINA1 are reported in various inflammatory diseases and acute kidney injury." (PMID 28522940, 2017). "Expression of SERPINA1 is up-regulated by acute kidney injury and can protect injured proximal tubule cells by reducing activity of neutrophil elastase." (PMID 25946105, 2015).
anemia (11 papers, 2017 to 2023). A reduction in the number of red blood cells, the amount of hemoglobin, and/or the volume of packed red blood cells. "Based on the current findings, we suggest that the SERPINA1 gene has a positive correlation with anemia as well as COPD, and the increase in altitude also influences the diseased conditions in a positive manner." (PMID 36320441, 2022). "The genetic polymorphic analysis of the SERPINA1 gene at the two specific locations rs28929474 and rs17580 gave a positive correlation between anemia, COPD, and mutated SERPINA1 in the current research work." (PMID 36320441, 2022). "The genetic analysis was performed in the SERPINA1 gene of anemia, COPD, and healthy individuals for the analysis of single nucleotide polymorphism at rs28949274 and rs17580 locations." (PMID 36320441, 2022). "Since the interrelationship between SERPINA1 and anemia has neither been studied nor been well-established, the novelty of the current findings is significant." (PMID 36320441, 2022). "Hence, it can be concluded that there is a genetic interlink between anemia and COPD with the SERPINA1 gene in common, as well as altitude has an influencing role in anemic and COPD conditions." (PMID 36320441, 2022).
lung adenocarcinoma (11 papers, 1992 to 2023). A carcinoma that arises from the lung and is characterized by the presence of malignant glandular epithelial cells. "Meanwhile, SERPINA1 expression was significantly lower in CHOL (cholangiocarcinoma), LIHC, LUAD (lung adenocarcinoma), and LUSC (lung squamous cell carcinoma)." (PMID 37511325, 2023). "Immunohistochemical studies revealed that patients with Serpina1-positive lung adenocarcinomas had a worse prognosis than Serpina1-negative ones." (PMID 18218118, 2008).
prostate carcinoma (11 papers, 2008 to 2025). A carcinoma that arises from epithelial cells of the prostate gland. "A proteomic analysis of the urine revealed APPs (FGA, FGG, HP, ITI4, SERPINA1) as biomarkers for prostate cancer, but the paper lacks the analysis of their pathophysiological role." (PMID 35328392, 2022). "Overexpression of alpha-1-antitrypsin (SERPINA1) promotes tumor progression in colorectal and gastric cancer, and its high level in plasma was observed in lung and prostate cancer patients." (PMID 39201484, 2024).
cholangiocarcinoma (10 papers, 2014 to 2025). A carcinoma that arises from the intrahepatic biliary tree (intrahepatic cholangiocarcinoma) or from the junction, or adjacent to the junction, of the right and left hepatic ducts (hilar cholangiocarcinoma). "For example, distinct peptide mass fingerprints (PMFs) were identified for early versus late recurrence in cholangiocarcinoma (CCA), where peptides such as KNTC1, DCLK1, ALG10, ATR, and BLM were associated with early recurrence, while SERPINA1, TGFB2, and SERPING1 were implicated in late recurrence." (PMID 41008874, 2025).
metabolic syndrome (10 papers, 2015 to 2025). A cluster of metabolic risk factors for CARDIOVASCULAR DISEASES and TYPE 2 DIABETES MELLITUS. "Further study of the effects of SerpinA1 on adipocyte and glucose metabolism may open the shade of metabolic syndrome in humans." (PMID 39532838, 2024).
Autoimmunity (9 papers, 2011 to 2025). The occurrence of an immune reaction against the organism's own cells or tissues. "Recent studies suggest that AAT has immunomodulatory effects, however, the contribution of SERPINA1 defective variants in autoimmunity is thoroughly obscure." (PMID 38791420, 2024).
cholestasis (9 papers, 2013 to 2025). Impairment of the bile flow caused by obstruction within the liver, or outside the liver in the bile duct system. "For example, colocalization analysis of acetylglucosaminylasparagine and cholestasis suggested a shared causal role of SERPINA1 p.Glu366Lys." (PMID 35347128, 2022). "By analogy with cholestasis observed in children with inherited AATD, we hypothesized the SERPINA1 PI*Z deficiency variant might be linked to a higher risk of cholestasis in pregnancy." (PMID 34557220, 2021). "Colocalizing these association signals increased the SPIP for cholestasis of pregnancy from 0.69 to 0.99, and the VPIP of SERPINA1 p.Glu366Lys from 0.37 to 0.80." (PMID 35347128, 2022).
Arthritis (8 papers, 2011 to 2022). Inflammation of a joint. "In this study, we characterized, a family with SERPINA 1 mutations with a variable deficiency in alpha-1 antitrypsin (AAT) and we questioned about a role in sensitizing to arthritis development in these patients." (PMID 35786784, 2022). "Furthermore, other authors reported clinical improvement of lupus-like disease and arthritis following administration of a fragment of SERPINA1 and SERPINA3, respectively, which, although belonging to different serpin subgroups, are sharing similar mechanisms of action with OV-SERPINS." (PMID 30254646, 2018).
liver cancer (8 papers, 1981 to 2025). An epithelial or non-epithelial malignant neoplasm that arises from the liver. "Antigenicity, molecular weight, subcellular localization and expression site predictions were used to shortlist liver cancer associated proteins including AMBP, CFB, CDHR5, VTN, APOBR, AFP, SERPINA1 and APOE." (PMID 39752339, 2025).
liver failure (8 papers, 2008 to 2025). A liver disease characterized by the liver losing or has lost all of its function. "However, the potential benefit of incorporating SERPINA1 sequencing into routine AATD screening may be higher in general populations with liver failure." (PMID 37651384, 2023).
obstructive lung disease (8 papers, 2012 to 2024). "First, alpha-1-antitrypsin (SERPINA1) is the best-known protein known to cause COPD as severe deficiency of alpha-1-antitrypsin results in obstructive lung disease." (PMID 38238732, 2024). "Adjusted odds ratios for developing airway obstruction (FEV1/FVC<0.7) and respiratory symptoms over 11 years of follow-up comparing different SERPINA1 genotypes." (PMID 22912729, 2012).
osteoporosis (8 papers, 2018 to 2024). A condition of reduced bone mass, with decreased cortical thickness and a decrease in the number and size of the trabeculae of cancellous bone (but normal chemical composition), resulting in increased fracture incidence. "A genetic association study identified SERPINA1 as a shared genomic region for C-reactive protein and osteoporosis." (PMID 39136019, 2024). "Furthermore, SERPINA1 gene therapy has been explored and evaluated in animal models of osteoporosis." (PMID 39136019, 2024).
schizophrenia (8 papers, 2013 to 2024). A major psychotic disorder characterized by abnormalities in the perception or expression of reality. "Recent studies indicate that Serpina1 is associated with various diseases, such as sporadic amyotrophic lateral sclerosis, cancers, schizophrenia, bipolar disorder, and frontotemporal dementia." (PMID 30791599, 2019). "The SERPINA1 gene, which encodes for the AAT protein has also been implicated in schizophrenia." (PMID 28974776, 2017).
Alzheimer disease (7 papers, 2014 to 2024). A progressive, neurodegenerative disease characterized by loss of function and death of nerve cells in several areas of the brain leading to loss of cognitive function such as memory and language. "Recently, SERPINA1 was reported to be a chaperone in amyloidoses, and it plays a role in amyloid aggregation, which may lead to the pathogenesis of amyloidotic diseases, for example amyotrophic lateral sclerosis (ALS), familial amyloid polyneuropathy (ATTR) and Alzheimer's disease." (PMID 33336526, 2021).
glaucoma (7 papers, 2014 to 2025). Increased pressure in the eyeball due to obstruction of the outflow of aqueous humor. "Moreover, the downregulation of SPTA1 (spectrin alpha, erythrocytic 1) and SERPINA1 (serpin family A member 1) was also confirmed in glaucoma patients in comparison to ICL and/or cataracts patients, as previously observed by mass spectrometry." (PMID 39000104, 2024).
glioblastoma (7 papers, 2014 to 2025). The most malignant astrocytic tumor (WHO grade IV). "Higher expression of SERPINA1 has been associated with a poor prognosis in patients with high-grade glioblastoma." (PMID 38021884, 2023). "The findings revealed that glioblastoma has higher SERPINA1 expression level than normal tissue (p < 0.05)." (PMID 36349191, 2022). "SERPINA1 expression had positive correlation with NQO1 expression in glioblastoma." (PMID 36349191, 2022).